IL6 (interleukin 6)
Diseases named in the same sentence as IL6 in open-access papers (continued):
Sharing a sentence is not in itself a finding about the gene and the disease.
tumor (continued). "In parallel with the most significant inhibition of IL-6 expression in ALDH− bulk tumor cells, miRNA array analysis unveiled that let-7a-2-3p is more robustly upregulated in ALDH− BCCs vs. ALDH+ CSCs following XIST KD." (PMID 36922677, 2023). "Our results are consistent with previous studies showing that lactic acid in the tumor-conditioned medium can orchestrate pro-tumoral cytokine production, such as IL-6." (PMID 36614179, 2023). "It was shown that hepatocyte-specific Tim-3 overexpression enhances tumor cell growth through IL-6 autosecretion, and it increases the metastasis-forming ability of HCC cells by promoting the epithelial-mesenchymal transition." (PMID 37567938, 2023). "The expression of interleukin-6 (IL-6) and nuclear factor kappa-B (NF-κB) was significantly higher in tumor tissues than normal tissues (P = 0.021 and P = 0.00072, respectively), suggesting more inflammation in tumor tissues than in normal tissues." (PMID 38021159, 2023). "The effects not only included enhanced T cell function following anti-PD-1 mAb failure but also decreases in the levels of tumor-promoting cytokines, such as IL-6 and progranulin." (PMID 37670328, 2023). "The elevated levels of SASP by senescent T cells, such as IL-6, IL-8, and IL-18, promote tumor development and suppress antitumor immunity, regulating the tumor microenvironment through proinflammatory and anti-inflammatory cytokines." (PMID 38087369, 2023). "The IL6-JAK-STAT3 signaling pathway promotes tumor invasive growth and suppresses the antitumor immune response." (PMID 36867313, 2023). "The COL6 ETP peptide was found to promote tumor inflammation by increasing macrophage recruitment and upregulating inflammatory factors such as IL-6 and TNF-α." (PMID 37476379, 2023). "Notable differences in the expression of leptin (LEP) and IL-6 (IL6) were observed between tumor bulk from obese and lean patients in the NST ER+/HER2− subgroup." (PMID 37479706, 2023). "The downregulation of the IL6 and IL12B cytokines and the IFNG responses in TNBC tumor samples were associated with significantly poor responses to neoadjuvant therapies that included olaparib." (PMID 37932806, 2023). "4T1 murine tumor cells secreted higher levels of inflammatory cytokines, such as IL6, IL8, RANTES, G-CSF, GM-CSF, IL-12, which can impact on MDSCs differentiation or cancer cells metastasis." (PMID 37268941, 2023). "The antitumor potential of M1-like TAMs is based on the lysis of tumor cells after phagocytosis or on the secretion of immunostimulatory cytokines and chemokines (e.g., IL-6, IL-12, TNF) which induce inflammation and thus tumor suppression." (PMID 36672212, 2023). "Patients with tumor cells expressing high IL-6 had a significantly shorter PFS than those with tumors producing less IL-6 (nhigh=24 vs nlow=35, median survival difference=81 days, p=0.039)." (PMID 37852738, 2023). "The dual role of IL-6 in HCC can be partly explained by the heterogeneity of the tumor microenvironment and the complex interplay between cancer cells, immune cells, and stromal cells." (PMID 37892997, 2023). "CAFs aggregate macrophages and activate the NF-κB pathway through the secretion of IL-6 and IL-8, resulting in tumor immunosuppression." (PMID 36793444, 2023). "The majority of DEGs were shared between cytokine blockade treatments, suggesting that TNFα, IL-1β, and IL-6 signaling converge on similar pathways in the tumor microenvironment." (PMID 37461742, 2023). "This is because it is known that loading DCs with tumor cell lysates positively regulates the expression of co-stimulatory surface molecules and increases the secretion of IL-6, IL-12 and TNF-α." (PMID 37048096, 2023). "XIST directly binds and suppresses let-7a-2-3p, a member of the let-7 family of miRNAs with tumor suppressor functions, leading to markedly elevated IL-6 production in ALDH- BC cells (BCCs) and, to a lesser extent, in ALDH+ CSCs." (PMID 36922677, 2023).
tumor (continued). "TUBB2B regulated the expression of TNF-a, IL-6, and PD-1/PD-L1 through the inhibit tumor invasion gene PER1." (PMID 37719786, 2023). "Hypoxia myeloid cells exhibit an MDSC phenotype with features including activation of STAT3 pathway, likely in response to tumor-secreted IL-6." (PMID 37694144, 2023). "In KRAS-mutant lung cancer, inhibiting MEK increases the expression of TGF-β, IL-6, and IL-23, promoting the differentiation of Th17 cells and the secretion of IL-17 and IL-22, thereby enhancing tumor resistance, invasiveness, and metastasis." (PMID 37680632, 2023). "First develop in the bone marrow, they then infiltrate and accumulate in solid tumors via factors such as GM-CSF, G-CSF, M-CSF, VEGF, IFN-γ, IL-6, and IL-4, which are secreted by tumor cells or other TME components." (PMID 37781367, 2023). "The IL-6 expression of tumor and T cells from patients with NSCLC (Korean cohort) was determined (see Study criteria of cohort #2 (Korean cohort))." (PMID 37852738, 2023). "In future studies, we intend to determine the expression levels of let-7a and IL-6 in serum and tumor tissues from the same patient cohort." (PMID 38114473, 2023). "Various inflammatory molecules like IL-6, TGF-β, IFN-γ, and TNF-α are associated with tumour development, while tumour recurrence is associated with its spread." (PMID 37742025, 2023). "Elevated levels of IL-6 in the serum of MM patients directly correlate with tumour burden and severity of disease." (PMID 37808081, 2023). "CRP is an acute reactive protein mainly produced in hepatocytes, which is regulated by proinflammatory cytokines such as interleukin 6, which contributes to the tumor microenvironment, and supports tumor angiogenesis, proliferation, growth, and metastasis." (PMID 36890182, 2023). "A study on TNBC indicated that simultaneous inhibition of IL-6 and IL-8 expression significantly inhibit tumor growth in vitro and in vivo." (PMID 37007080, 2023). "We then added neutralizing antibodies against CCL18, IL-6 and IL-8 to NBFs treated with fresh chemoresistant tumor CM." (PMID 36418470, 2023). "Inhibition of IL-6/G-CSF/MEK1/2 shifted the immune cell landscape towards an anti-tumour profile, suggesting that these pathways also instruct a pro-tumourigenic immune TME." (PMID 37703292, 2023). "IL-6 activates the corresponding receptor IL-6R on tumour cells and CAFs by means of autocrine–paracrine, which leads to differential activation of the STAT3 and MEK/ERK signalling pathways, resulting in tumour development." (PMID 37927475, 2023). "Viral IL-6 is also expressed at physiologically functional levels in latently infected cells and is detectable in the sera and/or tumor tissues of patients with KS, PEL, and MCD." (PMID 37883374, 2023). "Our RNAseq analyses indicated IL-6 as the gene most significantly inhibited in ALDH− bulk tumor cells upon XIST KD, although this gene is also downregulated in ALDH+ CSCs." (PMID 36922677, 2023). "Components of the SASP, such as IL-6 and IL-8, also reinforce growth arrest and senescence in some senescent cells, thus controlling the tumor volume." (PMID 37190127, 2023). "Inflammatory cytokines such as IL-1 and IL-6 can activate estrogen or androgen receptor signaling on tumor cells, linking inflammation to tumor growth and endocrine resistance." (PMID 38033495, 2023). "Though the infiltrating Ly6G+ NPs and Ly6C+ monocytes (Ly6C+ Mos) were comparable between the tumour tissues of WT and KO mice, the expression of IL‐6 was moderately reduced in the infiltrating Ly6G+ NPs and Ly6C+ Mos." (PMID 36419386, 2023). "Studies have observed that IL-6 expression in patients with GBM accelerated tumor progression and affected patient prognosis." (PMID 37627528, 2023). "The percentage decrease in serum let-7a levels and the percentage increase in serum IL-6 were inversely correlated with tumor regression." (PMID 38114473, 2023).
tumor (continued). "IL-6 can also be produced by the tumor cells and secreted to interact with the IL-6 receptor on lymphatic endothelial cells (LECs) inducing production of the chemokine CCL-5." (PMID 36768435, 2023). "Several inflammatory factors related to tumours, including interleukins (IL-6, IL-10, IL-17, IL-1β), TGF-β, IFN-γ, TNF-α, VEGF, and MMPs, are also the cancer-associated genes." (PMID 37742025, 2023). "IL-6 is believed to play essential roles in tumor behavior by influencing cell survival and proliferation, migration and invasion, angiogenesis and metastasis." (PMID 37371050, 2023). "The role of cytokines in cancer, including OSCC, has been studied extensively and the main effector molecules regulating the pro-tumor immune activity are CSF-1, IL-6, VEGF, PGE-2, TGF-β and IL-10." (PMID 37568595, 2023). "Further GSEA analysis of tumor hallmarks indicated that oncogenic pathways, including IL6/JAK/STAT3 signaling, KRAS signaling, and Wnt/β‐catenin signaling pathway were engaged in the high‐risk group." (PMID 37334893, 2023). "The production of IL-6 is strongly related to the progression and development of several different types of tumors, possibly due to its ability to promote the growth of tumor cells and to favor angiogenesis in an inflammation-dependent context." (PMID 37174010, 2023). "Mechanistically, TRIM29 functioned as a positive regulator of tumor suppressor gene ZNF750 via modulating IL6/STAT3 signaling pathway." (PMID 37365152, 2023). "Several tumor-originated cytokines, such as IL-6, IL-1β, GM-CSF, G-CSF, VEGF, and MCP-1, have been reported to induce MDSC accumulation in preclinical models of HCC." (PMID 36845131, 2023). "In this model, aberrantly expressed XIST in ALDH− bulk tumor cells sequesters or antagonizes let-7a-2-3p in the nucleus, blocking its repression of IL-6 protein expression." (PMID 36922677, 2023). "IL-6 is a multifunctional nuclear factor κB-regulated cytokine that acts as a critical tumor promoter during early CRC tumorigenesis." (PMID 36572816, 2023). "Many studies have shown the very important role of IL-6 signalling pathway activity in the biology of malignant tumours." (PMID 38098074, 2023). "IL1RN and IL10 have anti-inflammatory functions, IL1 promotes inflammation, carcinogenesis and anti-tumor immunity, IL6 is pro-tumoral by activating carcinogenesis and tumor outgrowth, and IL10 promotes cytotoxicity but inhibits anti-tumor activities." (PMID 37465363, 2023). "Correlation analysis for the proportion of tumor infiltration macrophages revealed that M2 was correlated with IL-6." (PMID 37124547, 2023). "As IL-6 and IL-8 act as key regulators of tumor progression and CSC activity, we focused on IL-6 and IL-8 in this study to determine their roles in mediating XIST regulation of ALDH+ E-CSCs." (PMID 36922677, 2023). "This has led to the preclinical and clinical development of various IL-6/STAT3 inhibitors targeting the IL-6/JAK/STAT3 components in order to inhibit tumor growth and reduce immunosuppression in the tumor microenvironment." (PMID 37762522, 2023). "The mechanism driving the development of hypoxia myeloid cells remains to be determined although prior work would suggest that it is through mesenchymal EPN tumor cell secretion of IL-6 and hypoxic conditions within the regions of necrosis." (PMID 37694144, 2023). "Inhibition of IL-6 normalizes the tumor vasculature and reduces the recruitment of immunosuppressive cells, such as Treg cells to abrogate resistance to anti-VEGF therapy." (PMID 36901858, 2023). "There was a significant correlation between tumor blood flow distribution type and serum IL-6 levels (r = 0.550, P < 0.001)." (PMID 37430251, 2023). "According to some studies, IL-6 can have indirect anti-tumor activity through Bcl-2 and immunoglobulin production, but also can stimulate cytokine secretion within the tumor and limit the effectiveness of immunotherapy." (PMID 37514190, 2023).
tumor (continued). "In the process of infection, trauma, surgery, stress reaction, tumor generation, and other acute inflammatory reactions, IL-6 will be rapidly generated." (PMID 37007019, 2023). "In addition, other substances released by the microbiota, such as pyridoxine, vitamin B, and ferrichrome, could affect cancer cells directly, causing apoptosis or modulating the tumor environments through cytokines, such as IL-6 and IFN-γ, leading to the maturation of regulatory T lymphocytes." (PMID 37111629, 2023). "While IL-6 has been documented as a tumor-supportive cytokine in this context, it is typically associated with M1 macrophages." (PMID 37240536, 2023). "According to literature data, IL-6 and IL-10 cytokines play a major role in the effects brought by macrophage activities in the tumor microenvironment." (PMID 37835437, 2023). "The relationship between tumor growth and IL6 signaling studied in orthotopic xenograft model demonstrated that S. mutans infection greatly increased glucose uptake, which is connected to accelerated tumor growth and EMT alterations." (PMID 38170015, 2023). "In contrast, combination therapy enhanced CTL responses in several tumor models, consistent with the inhibitory effect of IL-6 on CTLs in vitro." (PMID 36599350, 2023). "IL-6 has physiological and pathological roles in inflammation and immunity and can promote tumor growth." (PMID 37569777, 2023). "Our data also revealed that high IL-6 levels in MBC patients are associated with a low proportion of CD8+ lymphocytes, which play a central role in anti-tumor immunity." (PMID 37733188, 2023). "The third most frequently implicated hallmark (14 proteins) was “tumor-promoting inflammation”, including markers such as CXCL9, CXCL13, CXL17, IL6, and IL2-RA." (PMID 37264016, 2023). "And it was shown that upregulation of albumin promotes tumor proliferation and metastasis via activating expression of tumor necrosis factor-α, interleukin-1, and interleukin-6." (PMID 37251954, 2023). "Interleukin-6 (IL-6), a cytokine produced by various cell types including immune cells, endothelial cells, and tumor cells, is known to strongly induce epithelial to EMT in HNSCC." (PMID 37907991, 2023). "The percentage of CD4+ Th1 was increased after anti-IL-6 treatment and cryo-thermal therapy compared with that in tumor-bearing control." (PMID 37108179, 2023). "IL-6 also down-regulates T lymphocyte apoptosis and maintains anti-tumour immunity in the lymph nodes, where lymphocyte priming takes place, and in the tumour microenvironment, where IL-6 promotes the recruitment of effector T lymphocytes." (PMID 37629081, 2023). "The authors found out that, due to iNOS activity, the classic Th2 response was completely (IL‐4 and IL-13) or markedly (IL‐5, IL‐6, IL‐9, and IL-10) inhibited after tumor irradiation." (PMID 37347290, 2023). "Low serum IL-6 levels enhance immune responses and inhibit the growth of cancer cells, whereas high serum IL-6 levels decrease immunity and enhance infiltration by tumor cells." (PMID 36693957, 2023). "In CLL cells, the constitutive activation of STAT-3 and NF-κB causes the delivery of IL-6, which further increases JAK2/STAT3 stimulation, leading to the IL-6/JAK/STAT3 feed-forward loop that controls tumor proliferation." (PMID 37048814, 2023). "IL-6 is considered to be the critical factor connecting the state of chronic inflammation with tumor progression." (PMID 37176160, 2023). "Patients who did not respond to ICI (pembrolizumab) had significantly higher median IL-6 tumor expression than those who responded to treatment." (PMID 37852738, 2023). "IL-6/STAT3 signaling has an important consequence on tumor-infiltrating immune cells in the tumor immune microenvironment in CRC." (PMID 36835094, 2023). "Several cytokines and growth factors expressed by our AFs, such as CXCL-12, IL6, FGFs and VEGFs, were shown to participate in CAFs/cancer cells crosstalk, and promote tumour progression." (PMID 37938546, 2023).
tumor (continued). "A blocking study revealed that M2 differentiation was caused by tumor-produced prostaglandin E2 (PGE2) and IL-6." (PMID 37234990, 2023). "We identified that miR-1246 is more abundant in high metastatic tumor EVs than in low metastatic ones, and that miR-1246 elucidated the mechanism of drug resistance acquisition by IL-6 secretion of ECs." (PMID 37124539, 2023). "This profile was retained when MPE tumor cells were cultured in the presence of autologous cell free fluid (CFF) or medium supplemented with IL-6 plus IL-8 or TGFβ." (PMID 37063842, 2023). "CAFs secrete cytokines such as TGF-β, IL-6, and CCL2, which promote the recruitment of monocytes and their differentiation into M2-type tumor-associated macrophages (TAMs)." (PMID 37165428, 2023). "We found that BC patients with Ta status primary tumour size were characterised by higher IL-6 expression than BC patients with T1 and ≥T2 status (p < 0.05)." (PMID 37047238, 2023). "HRS cells expressed IL‐6, which exerted as autocrine or paracrine to promote tumor cell growth by triggering the activation of JAK/STAT3 signaling, which was essential for the development of cHL." (PMID 38020717, 2023). "It inhibits the activation of inflammasomes mediated by NF-κB, TNF-α and mitochondrial autophagy, resulting in reduced secretion of IL-1β and IL-6, thereby delaying the progression of colon cancer and reducing the tumor load." (PMID 37020871, 2023). "IL-10 can stimulate pro-tumor neutrophils to produce PD-L2, which inhibits T cells, while IL-6 can enhance this process." (PMID 37496019, 2023). "The study also found that myoferlin knockdown significantly reduced IL-6-mediated tumor cell migration, tumor sphere formation, and the population of cancer stem cells in vitro." (PMID 37538852, 2023). "IL-6 has been shown to promote various aspects of tumor progression, such as cell growth, EMT, migration, invasion, and metastasis." (PMID 37511415, 2023). "As JAKs are activated by cytokine receptors and several studies proposed autocrine IL-6 signaling in tumor cell lines, we envisaged an autocrine activity of IL-6 produced by BCR-stimulated neonatal CD19+CD43- B cells." (PMID 36735294, 2023). "IL6 was a potent pro-tumor stimulator and strongly interacted with other hub genes in the SIPS network." (PMID 37658364, 2023). "Excessive secretion of IL-6 by tumor cells or mesenchymal cells in TME has been demonstrated to promote tumor growth, metastasis, and therapeutic resistance in multiple tumors, including BC." (PMID 37127625, 2023). "Yang and colleagues demonstrated that the combination of IL-6 inhibition with CD40 stimulation reversed M2-mediated tumor immunosuppression, sensitized tumors to checkpoint blockade, and extended animal survival in two syngeneic GBM models." (PMID 37762522, 2023). "Interleukin-6 (IL-6) as a cytokinereleased by various cells such as cancerous cells contributed to the expansion anddifferentiation of tumor cells." (PMID 40636894, 2023). "A report on lung tissue and serum demonstrates that DEN treatment increased COX-2, TNF-α, and IL-6 levels, while others have shown elevated tumor markers (e.g., carcinoembryonic antigen, CEA)." (PMID 37259369, 2023). "Analysis of fluorescence-activated cell sorting (FACS)-purified tumor populations (EMT6 cells, T cells, myeloid cells, and fibroblasts) identified inflammatory Ly6C+ cancer-associated fibroblasts as the main IL-6 producers, consistent with prior studies." (PMID 36599350, 2023). "Here, we set out to investigate this issue by taking advantage of advanced cell culture models and illuminating the interplay between TNBC tumor cells and associated fibroblasts, dissecting the contribution of TGF-β, PDGF and IL-6." (PMID 37173963, 2023). "These tumor suppressor cells, such as cytotoxic T lymphocytes, also upregulate the release of pro-inflammatory cytokines, namely, IL-2, IL-6, IL-12, INF-γ, and TNF-α." (PMID 37238966, 2023).